LRG1 (leucine rich alpha-2-glycoprotein 1)
Diseases named in the same sentence as LRG1 in open-access papers (continued):
Sharing a sentence is not in itself a finding about the gene and the disease.
endothelial dysfunction (6 papers, 2017 to 2024). In vascular diseases, endothelial dysfunction is a systemic pathological state of the endothelium (the inner lining of blood vessels) and can be broadly defined as an imbalance between vasodilating and vasoconstricting substances produced by (or acting on) the endothelium. "Levels of EGF, LRG1, and Angpt-2, evaluated as endothelial dysfunction biomarkers, are increased in DNE children and adolescents." (PMID 39311327, 2024). "In fact, LRG1 has been shown to promote cardiovascular disease by regulating endothelial dysfunction and inflammation through TGF-β and SMAD1/5/8 signaling in endothelial cells, interrupting normal endothelium-dependent vasodilation and availability of nitric oxide." (PMID 38745756, 2024). "Upregulated LRG1 in turn may contribute to the development of a destabilized vasculature with prominent endothelial dysfunction and vascular leakage during impaired lung tissue wound healing." (PMID 38745756, 2024). "The authors speculate that LRG1 levels might be systemically increased only in the early stage of cardiovascular disease, which is characterized by arterial stiffening and endothelial dysfunction, while declining during disease progression." (PMID 35062948, 2022). "Thus, myofibroblast-derived LRG1 may contribute to endothelial dysfunction in the retina in a paracrine manner, but it may also be involved in promoting retinal fibrosis through autocrine mechanisms." (PMID 38745756, 2024). "However, it is not clear whether the up-regulated expression of LRG1 was the cause or the consequence of endothelial dysfunction." (PMID 34291056, 2021).
Hyperglycemia (6 papers, 2021 to 2025). An increased concentration of glucose in the blood. "In mouse models, we observed that Lrg1-knockout protects mice from developing hyperglycemia-induced early vascular dysfunction and associated impairment of the ERG b-wave." (PMID 41124286, 2025). "Retinal hyperpermeability, evaluated by fundus fluorescein angiography, showed increased dye leakage and loss of intracapillary fluorescein only in wild-type Lrg1+/+ STZ mice after 6 months of hyperglycemia, whereas retinal permeability in Lrg1-/- mice was unchanged at all 3 time points studied." (PMID 41124286, 2025). "Together, these findings demonstrate that LRG1 is required for the onset of hyperglycemia-induced early capillary dysfunction and provide evidence that LRG1-driven early vascular changes are sufficient to have a negative impact on retinal function." (PMID 41124286, 2025). "Following 6 months of hyperglycemia, we found LRG1 protein increased in the retinas of diabetic mice compared to controls." (PMID 41124286, 2025). "We found LRG1 in the plasma of control mice and elevation after 5 months of hyperglycemia, with possible contribution from a small increase in liver Lrg1 expression." (PMID 41124286, 2025). "In both models, we observed a time-dependent increase in Lrg1 transcript in the retinas, evident after 2 and 4 months of hyperglycemia, in the STZ and Ins2Akita mice respectively." (PMID 41124286, 2025). "In this study, we showed that hyperglycemia-induced LRG1 acts on pericytes to trigger early vascular anomalies, initiating retinal dysfunction." (PMID 41124286, 2025). "Lastly, it was reported that hyperglycemia results in leucine-rich α-2-glycoprotein 1 (LRG1) overexpression, which promotes angiogenesis and GEC injury by TGF-β/activin receptor-like kinase 1 (ALK1) pathway." (PMID 37685845, 2023). "The deletion of LRG1 diminishes the deteriorating effects of hyperglycemia, such as albuminuria, endothelial injury, and podocyte damage." (PMID 37685845, 2023). "To determine whether the diabetic retina contributes to the ectopic expression of Lrg1, and to assess whether this is a direct consequence of hyperglycemia, we employed the streptozotocin (STZ) and the Ins2Akita mouse models." (PMID 41124286, 2025). "Our observations that the hyperglycemia-induced PBs, reported to be an early sign of diabetic vascular pathology, and phosphorylation of MLC are attenuated in the Lrg1 knockout mouse provide evidence that LRG1 induction is an initiating event." (PMID 41124286, 2025). "We found that LRG1 acts through LPHN2 to induce both angiogenic and neurotrophic processes in hyperglycemia." (PMID 35562586, 2022).
Insulin resistance (6 papers, 2022 to 2024). Increased resistance towards insulin, that is, diminished effectiveness of insulin in reducing blood glucose levels. "LRG1 has been linked to mediating insulin resistance, possibly by downregulating the expression of insulin receptor substrate 1 and 2 (IRS1 and IRS2) in hepatocytes." (PMID 35955698, 2022). "LRG1 plays a key role in diet-induced hepatosteatosis and insulin resistance by mediating the crosstalk between adipocytes and hepatocytes." (PMID 35955698, 2022). "LRG1 also plays an important role in the development of hepatic steatosis and insulin resistance." (PMID 39595649, 2024). "LRG1 is an adipocytokine related to insulin resistance and angiogenesis." (PMID 39670237, 2023). "Specifically, it was shown that the elevated levels of LRG1 in circulation, which are produced by adipocytes, can interfere with or compromise the function of hepatocytes and hence participate in the development of insulin resistance and hepatosteatosis." (PMID 35955698, 2022). "Although LD is often associated with hepatic steatosis and insulin resistance, we could not find a significant difference in the serum levels of LRG1 between LD patients and the age-, BMI-, and sex-matched healthy controls." (PMID 39595649, 2024). "This indicates that, in contrast to other metabolic and inflammatory diseases, circulating LRG1 is not a main marker of inflammation and insulin resistance in patients with LD." (PMID 39595649, 2024).
leukemia (6 papers, 2015 to 2024). A malignant (clonal) hematologic disorder, involving hematopoietic stem cells and characterized by the presence of primitive or atypical myeloid or lymphoid cells in the bone marrow and the blood. "LRG1 was found to be important in hematological diseases, and the association was primarily with leukemia." (PMID 35095520, 2021). "Commonly discussed in cancers, LRG1 reduction is surveyed to inhibit cell viability and promote apoptosis of leukaemia cells." (PMID 32975015, 2020). "The silencing of LRG1 could reduce viability and promote apoptosis in leukemia KASUMI-1 cells through regulating cyclin and apoptosis-related proteins." (PMID 35095520, 2021). "On hematological diseases cellular model, healthy hematopoietic stem progenitor cells overexpressed the leukemia stem cell-specific genes LY86, LRG1, and PDE9A under the induction of leukemia microvesicles." (PMID 35095520, 2021). "Moreover, healthy hematopoietic stem progenitor cells (HSPCs) can be transformed genetically by leukemia macrovesicles to over express LSC specific genes, which contains LY86, LRG1 and PDE9A and so on." (PMID 33604283, 2020).
renal fibrosis (6 papers, 2020 to 2025). A final common manifestation of a wide variety of chronic kidney diseases characterized by glomerulosclerosis and tubulointerstitial fibrosis. "Tubular epithelial cell derived LRG1 has been shown to activate the TGF-β-SMAD3 pathway in fibroblasts resulting in increased renal fibrosis." (PMID 38745756, 2024). "LRG1 is a novel pro-angiogenic factors involved in the abnormal angiogenesis and renal fibrosis in DN." (PMID 32982792, 2020). "In addition, leucine-rich α-2 glycoprotein 1 (LRG1) is elevated in renal fibrosis and promotes renal fibrosis through the TGF-β1/Smad3 signaling pathway." (PMID 40225869, 2025).
Stroke (6 papers, 2021 to 2025). Sudden impairment of blood flow to a part of the brain due to occlusion or rupture of an artery to the brain. "A study by Jin's group demonstrated an association between elevated LRG1 levels and increased infarction volume, stroke severity, and poor prognosis in patients with supratentorial cerebral infarction." (PMID 40549882, 2025). "LRG1 is an important factor in pathogenic angiogenesis, a critical stage in the development of neurological diseases such as stroke." (PMID 36959823, 2023). "Interestingly, high circulating LRG1 levels have been found positively associated with stroke severity and poor functional outcomes, as well as with poor cognitive impairment and neurological function." (PMID 38745756, 2024). "De novo vessel formation was confirmed, with CD34 staining showing significantly increased microvessel density after stroke, which again correlated with LRG1 expression." (PMID 38745756, 2024). "For instance, while some authors have measured higher levels of LRG1 in the plasma of patients with stroke compared to healthy controls, others have reported the opposite in the same clinical condition." (PMID 35062948, 2022). "There were relatively comprehensive clinical and basic studies on the function of LRG1 in stroke diseases." (PMID 35095520, 2021). "Apolipoprotein CII, LRG1, and C-reactive protein expression were significantly downregulated in poststroke depression relative to stroke subjects." (PMID 35095520, 2021). "Notably, the Neu_0 subgroup predominated among stroke neutrophils at 1 h, 24 h, and 7 days, exhibiting heightened expression of chemotactic genes such as Lrg1, Fos, Sell, Lfb, and S100a8." (PMID 38988493, 2024). "LRG1 significantly enhances apoptosis and autophagy during tMCAO, and a positive correlation was shown between LRG1 and severity in patients with cardiogenic embolic stroke." (PMID 36959823, 2023). "In patients with supratentorial cerebral infarction, higher LRG1 serum levels correlate positively with infarction volume and stroke severity, suggesting that LRG1 might indeed worsen ischemia/reperfusion injury." (PMID 35062948, 2022). "By the PRM validation, IGHA1, LRG1, IGHV3-64D, and CP may be biomarkers of neurological recovery after stroke." (PMID 36959823, 2023). "In addition, IGHA1, LRG1, IGHV3-64D, and CP are upregulated in patients with ischemic stroke and downregulated after rehabilitation, which may be used as biomarkers to monitor neurological impairment and recovery after stroke." (PMID 36959823, 2023).
viral infection (6 papers, 2009 to 2025). "LRG (leucine-rich alpha-2-glycoprotein-1) is a protein involved in an the acute-phase response to bacterial or viral infection, or the initiation of granulocyte differentiation." (PMID 29642865, 2018). "IFN-stimulated genes (ISGs), including CRP, IFIT1, LRG1, SLC1A1, and CDKN1A, were upregulated during HBoV1 infection, suggesting that viral infection elicited an antiviral response from the host cell." (PMID 39846742, 2025).
biliary tract cancer (5 papers, 2015 to 2024). "LRG1 is overexpressed in several types of carcinomas, including pancreatic, bladder, ovarian, and biliary tract cancer." (PMID 26856989, 2016). "The precise function of LRG1 remains unknown, but accumulating evidences showed that LRG1 is closely correlated with various types of cancers, such as lung, oral, ovarian, gastrict, pancreatic and biliary tract cancers." (PMID 32252660, 2020).
colitis (5 papers, 2018 to 2023). Inflammation of the colon. "Twenty-eight genes exhibited overlap between both datasets, which included Lcn2 and Lrg1, pro-inflammatory genes previously implicated in colitis." (PMID 30455703, 2018). "However, in IL-6 deficient mice treated with lipopolysaccharide or induced colitis, LRG1 increase can still be observed, suggesting there may be an IL-6 independent mechanism to upregulate LRG110." (PMID 32249825, 2020). "For instance, a substantial increase in Lrg1 expression was observed in mouse models with inflammation of the cystic fibrosis intestine and severe colitis." (PMID 35062948, 2022).
diabetic retinopathy (5 papers, 2022 to 2024). "Unpublished data from our lab are also suggestive of a direct effect of LRG1 on pericytes, both in the context of early-stage diabetic retinopathy (DR) and in the context of pathological neovascularisation." (PMID 34987199, 2022). "Previous studies have identified LRG1 as a new proangiogenic gene that enhances cancer growth and diabetic retinopathy." (PMID 36276281, 2022). "For instance, LRG1 promotion of pathological angiogenesis has been described in animal models of diabetic retinopathy and kidney disease with retinal and glomerular endothelial cells being the source of LRG1, respectively." (PMID 35062948, 2022). "In diabetic retinopathy, where retinal vascular dysfunction, dropout and neovascularization are prominent, LRG1 has been reported to be upregulated not only in the vitreous humour and in ocular tissues, but also systemically in the plasma of patients with proliferative diabetic retinopathy (PDR)." (PMID 38745756, 2024). "Thus, targeting TGF-β or LRG1 may have a positive impact in halting the development and progression of diabetic retinopathy." (PMID 39845838, 2024). "LRG1 induces angiogenesis via TGF-β during the development and progression of diabetic retinopathy." (PMID 39845838, 2024). "In addition, unpublished data from our lab shows that LRG1 can promote the phenotypic and functional differentiation of pericytes towards a fibrotic state and that this contributes to vascular dysfunction in diabetic retinopathy through both canonical and non-canonical TGF-β signaling." (PMID 38745756, 2024).
emphysema (5 papers, 2022 to 2024). "In particular, in human COPD tissue, upregulated LRG1 was localized specifically to the endothelium and correlated positively with marked airflow obstruction, decline in lung function and severity of emphysema." (PMID 38745756, 2024). "The conditional knockout of LRG1 from endothelial cells reduced emphysema in mice." (PMID 38707515, 2024). "Deletion of LRG1 may reduce or partially reverse the severity of emphysema in model mouse by inhibiting the apoptosis of PMVECs." (PMID 38707515, 2024). "In addition, recent research is suggestive for a link between Lrg1 expression and emphysema and inhibition of Lrg1 protected endothelial cells from vascular rarefaction (= malperfusion of vessels) and alveolar damage." (PMID 37932771, 2023). "They further demonstrated that conditional deletion of Lrg1 in endothelial cells is sufficient to rescue the phenotype of lung vessels and organ functionality in a mouse model of emphysema, formally proving that LRG1 drives tissue malfunction through destabilization of the endothelial compartment." (PMID 35062948, 2022). "However, the mechanism of the deletion of LRG1 from endothelial cells rescued by COPD or emphysema remains unclear." (PMID 38707515, 2024). "However, the mechanism of the deletion of LRG1 from endothelial cells rescued by cigarette smoke (CS) induced emphysema remains unclear." (PMID 38707515, 2024).
esophageal squamous cell carcinoma (5 papers, 2020 to 2024). Esophageal squamous cell carcinoma (ESCC) is a type of esophageal carcinoma (EC) that can affect any part of the esophagus, but is usually located in the upper or middle third. "For esophageal squamous cell carcinoma, a significant relationship between LRG1 expression and T stage, M stage, and poor prognosis has been reported, suggesting that LRG1 is associated with the malignant potential of various cancers." (PMID 38658967, 2024). "Apoptosis effected by LRG1 was also shown in a study of human esophageal squamous cell carcinoma by a decrease in bcl-2 and increases in Bax and caspase 3 expression when LRG1 was overexpressed by LRG1 transfection and opposite levels as a consequence of LRG1 RNA silencing." (PMID 34692699, 2021).
fibrosis (5 papers, 2011 to 2023). the formation of excess fibrous connective tissue in an organ or tissue in a reparative or reactive process. "It will be interesting to investigate whether the inhibition of LRG1 would mitigate the joint fibrosis-related symptoms, thus helping to maintain better gait and improving the lifestyle of patients with OA." (PMID 36569927, 2022).
glioblastoma (5 papers, 2015 to 2021). The most malignant astrocytic tumor (WHO grade IV). "For isocitrate dehydrogenase one wild-type glioblastoma, high expression of LRG1 was regarded as an independent factor." (PMID 35095520, 2021). "The plasma concentrations of LRG1, C-reactive protein, and complement component C9 showed significant positive correlations with tumor size in glioblastoma patients." (PMID 35095520, 2021). "The levels of pro-apoptotic Bax and cleaved caspase-3 were enhanced, and Bcl-2 expression was downregulated from leucine-rich α2 glycoprotein 1 (LRG1)-silencing, which inhibited the growth of xenograft tumors and induced apoptosis of U251 glioblastoma cells in vitro and in vivo." (PMID 30201893, 2018). "The stable knockdown of LRG1 has been reported to promote the apoptosis of glioblastoma cells." (PMID 28376129, 2017).
glioma (5 papers, 2016 to 2024). A benign or malignant brain and spinal cord tumor that arises from glial cells (astrocytes, oligodendrocytes, ependymal cells). "LRG1 can also modulate the invasion and migration of glioma cell lines through the TGF-β signaling pathway." (PMID 32337221, 2020). "A recent study showed that LRG1 promoted proliferation, migration and invasion of glioma cells, as well as downregulated the expression of E-cadherin." (PMID 26856989, 2016). "A recent study showed that LRG1 overexpression activated the canonical TGF-β signaling pathway and enhanced the invasiveness of glioma cells, which could be reversed by TGF-β signaling pathway inhibitor." (PMID 26856989, 2016).
lymph node metastasis (5 papers, 2016 to 2025). "Here, high LRG-1 levels were associated with a decreased disease-free survival (HR 2.090, 95%CI: 1.205–3.625; p = 0.009) as well as lymph node metastasis and histological grade." (PMID 38413424, 2024). "LRG1 expression was significantly correlated with deeper invasion depth (P = 0.032) and lymph node metastasis (P = 0.013)." (PMID 26856989, 2016). "We statistically analyzed the relationships between recurrence risk, BRAF gene mutation, gender, age at first thyroid cancer diagnosis, tumor size, extrathyroidal invasion, lymph node metastasis, and distant metastasis as well as the expression levels of PROS1, CLU, and LRG1." (PMID 40797389, 2025). "Among these NSCLC patients, patients with lymph node metastasis had higher exosomal LRG1 expression than patients without lymph node metastasis." (PMID 35158999, 2022). "In addition, LRG1 expression was stronger in tumors without lymph node metastasis compared with N + tumors (p = 0.025)." (PMID 38898137, 2024). "PTC patients with lymph node metastasis showed significantly lower IHC scores for PROS1 (P < .001), CLU (P = .003), and LRG1 (P < .001) than patients without metastasis, respectively." (PMID 40797389, 2025).